HES1 (hes family bHLH transcription factor 1)
Diseases named in the same sentence as HES1 in open-access papers (continued):
Sharing a sentence is not in itself a finding about the gene and the disease.
squamous cell carcinoma (2 papers, 2013 to 2023). A carcinoma arising from squamous epithelial cells. "To answer this question, we ran an immunohistochemical study of Notch1 and Hes-1 in a series of human squamous cell carcinomas collected in a high-risk area in China." (PMID 23409141, 2013). "Except for the endometrium, HES1 was also estimated as a transcription factor in squamous cell carcinoma tissue, kidney IRI and Sham disease model, and lymph tissue, which has been reported as one of the downstream effectors of the Notch signaling pathway." (PMID 36243975, 2023).
synovial sarcoma (2 papers, 2020 to 2023). "Several other genes pertaining to these networks may be dysregulated in synovial sarcoma, including LEF1, AXIN2, TCF7, and FZD homologues in the Wnt/β-catenin, HES1, and NOTCH1 in the Notch, as well as SMO and PTCH in the Sonic Hedgehog pathways." (PMID 32322158, 2020).
T cell lymphomas (2 papers, 2009 to 2023). "In contrast, overexpression of Hes1 caused T cell lymphoma with a longer latency and lower penetrance." (PMID 19688092, 2009). "Here, we show that ectopic expression of Hes1 predisposes mice to develop T cell lymphoma, which suggests that Hes1 up-regulation by Notch signaling is one of the components involved in Notch-mediated tumorigenesis." (PMID 19688092, 2009). "Collectively, elevation of different subsets of Notch target genes appears to occur in these T cell lymphomas of Hes1 transgenic mice." (PMID 19688092, 2009). "T cell lymphomas were found in greater than 25% of either the H5 or H12 line of Hes1 transgenic mice with an average age of onset of 20 weeks." (PMID 19688092, 2009). "Does this mean that T cell lymphoma resulting from constitutive Notch signaling involves both up-regulation of Hes1 and down-regulation of E protein function?" (PMID 19688092, 2009). "We find that constitutive expression of Hes1 in the thymus leads to T cell lymphomas with low efficiency." (PMID 19688092, 2009). "However, expression of Hes1 significantly shortens the latency of T cell lymphoma developed in Id1 transgenic mice, where the function of bHLH E proteins is inhibited." (PMID 19688092, 2009). "However, Hes1 promotes rapid tumorigenesis in a well-studied model of T-ALL in which expression of Id1 inhibits the function of E2A and HEB transcription factors, whose deficiency leads to T cell lymphoma." (PMID 19688092, 2009). "Interestingly, the T-cell lymphomas had expression of Notch1 and Hes1 similar to the DN3 stage rather than the DN4 stage." (PMID 37160922, 2023).
thyroid cancer (2 papers, 2018 to 2024). "It is noteworthy that the last study showed novel loci containing genes that were previously implicated in thyroid cancer (e.g., HES1, SPATA13, DIRC3, ID4) and a positive association of TSH with VEGFA expression, therefore angiogenesis." (PMID 39767631, 2024).
uveal melanoma (2 papers, 2022 to 2025). A melanoma derived from melanocytes of the uveal tract. "It is worth noting that primary uveal melanomas also display significant expression of HES1 and HES4 as well as of HEY1-2 and HEYL." (PMID 35673577, 2022). "JAG2, another NOTCH ligand whose effect may involve HES1 and HEY1, is also critically required for uveal melanoma cell proliferation and motile ability 59,60." (PMID 35673577, 2022).
abortion (1 paper, 2023). the ending of pregnancy by removing a fetus or embryo before it can survive outside the uterus. "qPCR was performed in placentas and the results showed decreased Jag1, Notch3 and Hes1 mRNA levels in LPS‐induced abortion mouse model compared with the control (n = 3/group)." (PMID 37272232, 2023). "In addition, GDF15 could serve as a pro‐invasive factor in human extravillous trophoblasts and upregulate JAG1/NOTCH3/HES1 pathway activity as well as rescue the embryo absorption phenotype observed in the LPS‐induced abortion mouse model." (PMID 37272232, 2023).
acute kidney injury (1 paper, 2022). Sudden and sustained deterioration of the kidney function characterized by decreased glomerular filtration rate, increased serum creatinine or oliguria. "Hes1 upregulation was found in acute kidney injury in an ischemia reperfusion model and correlated with the Notch signaling pathway." (PMID 35633893, 2022).
acute leukemia (1 paper, 2013). A clonal (malignant) hematopoietic disorder with an acute onset, affecting the bone marrow and the peripheral blood. "In addition Hes1 is highly expressed in blast-crisis CML and retroviral co-expression of Hes1 with BCR-ABL in a murine model led to an aggressive acute leukemia." (PMID 23675967, 2013).
adenoid cystic carcinoma (1 paper, 2018). A malignant tumor arising from the epithelial cells. "HES1 expression was absent or very low in normal salivary gland tissues; however, HES1 expression was high in adenoid cystic carcinoma tissues (P < 0.001)." (PMID 29665790, 2018).
adenosquamous carcinoma (1 paper, 2014). A carcinoma composed of malignant glandular cells and malignant squamous cells. "We detected MAML2 rearrangement using fluorescence in situ hybridization (FISH) in tissue samples from 42 cases of PMEC and 40 of adenosquamous carcinoma (ASC), and the expression of potential downstream targets of MECT1-MAML2, including HES1, FLT1 and NR4A2 with immunohistochemistry (IHC)." (PMID 24714697, 2014).
allergic disease (1 paper, 2025). An immune response that occurs following re-exposure to an innocuous antigen, and that requires the presence of existing antibodies against that antigen. "Further research is warranted to elucidate the specific mechanisms of action of NICD and Hes1 in allergic reactions, with the aim of identifying novel targets and strategies for the treatment of allergic diseases." (PMID 40870825, 2025).
angiomyolipoma (1 paper, 2017). A neoplasm with perivascular epithelioid cell differentiation often associated with tuberous sclerosis. "The loss of Tsc1 in mouse embryo NTs leads to the accumulation of NSCs, inhibition of differentiation, and increased oscillation of Hes1 and Rheb expression, consistent with our findings in angiomyolipoma cells." (PMID 29184052, 2017). "Since oscillation of Notch maintains multipotent NSCs, we propose that the Rheb-Notch-Rheb loop, controlled by fluctuations in the binding of Notch1 to Rheb-activating and Hes1-activating NREs, contributes to maintaining multipotent properties of angiomyolipoma cells." (PMID 29184052, 2017). "We used chromatin immunoprecipitation qPCR (ChIP-qPCR) to examine the binding of Notch1 to the promoter of Rheb and Hes1 (as a positive control) in angiomyolipoma cells in Dulbecco’s modified Eagle’s medium (DMEM) to identify which sites are functionally important and correspond to true NREs." (PMID 29184052, 2017). "We hypothesized that alterations in RHEB and HES1 expression are required for neuronal differentiation of angiomyolipoma cells." (PMID 29184052, 2017). "We propose that decreased binding of Notch1 to NREs may lead to suppression of Rheb and Hes1 expression and decreased oscillation, leading to sustained, low level of Rheb and Hes1, followed by neuronal differentiation of angiomyolipoma cells." (PMID 29184052, 2017). "We used a genetic strategy for cell-specific depletion of Tsc1 in the mouse embryo NT because expression of ID1 and ID3 was suppressed in angiomyolipoma cells in N-medium, Id proteins as well as high level of Hes1 prevent neurogenesis in NT50, 51, and Id3 and Hes1 are regulated by Notch154." (PMID 29184052, 2017). "However, both angiomyolipoma cell lines 621–101 and CRL4004 used in this work have multiple common features such as mTORC1 hyperactivation, differentiation abnormalities, binding of Notch1 to the RHEB and HES1 promoters, and oscillation of RHEB and HES1 mRNAs and proteins." (PMID 29184052, 2017).
Arthritis (1 paper, 2019). Inflammation of a joint. "In collagen II-induced murine arthritis and spontaneous arthritis in Hes1-GFP/TNF-transgenic mice, inhibited M1 polarization and simultaneously enhanced M2 polarization of Mφ significantly reduced the inflammatory response in the knee joints." (PMID 31178867, 2019).
autism (1 paper, 2024). Persistent deficits in social interaction and communication and interaction as well as a markedly restricted repertoire of activity and interest as well as repetitive patterns of behavior. "In a recent study, Yanan Deng reported that inhibition of the Notch pathway using DAPT alleviated autism-like behaviors and reduced NRG1 and phosphorylated ErbB4 levels, suggesting the involvement of the Notch1/Hes1 pathway in regulating the NRG1/ErbB4 pathway in autism." (PMID 38791584, 2024).
autoimmune disease (1 paper, 2019). A disorder resulting from loss of function or tissue destruction of an organ or multiple organs, arising from humoral or cellular immune responses of the individual to their own tissue constituents. "It has been established that IFN-γ signaling acts downstream of notch signaling in HSC development and that IFN-γ could disrupt the expression of Notch target genes HES1 and HEY1 in patients with autoimmune diseases." (PMID 31311586, 2019).
Barrett esophagus (1 paper, 2015). Esophageal lesion lined with columnar metaplastic epithelium which is flat or villiform. "It has been shown that loss of members of the TGFβ signaling cascade, such as Smad4 and β2 spectrin, can contribute to the initiation of Barrett's esophagus and the progression to esophageal adenocarcinoma through concomitant upregulation of Notch targets Hes1 and Jagged1." (PMID 26447543, 2015).
bile duct cancer (1 paper, 2021). "Interestingly, an increased expression of HES1 triggered by pancreatic stellate cells leads to a resistance to gemcitabine, a drug with high relevance in the therapy of PDAC and bile duct cancer." (PMID 33498866, 2021).
Caroli disease (1 paper, 2023). Caroli disease (CD) is a rare congenital liver disease characterized by non-obstructive cystic dilatations of the intra-hepatic and rarely extra-hepatic bile ducts. "In these rats, increased JAG1 expression in myofibroblasts was accompanied by elevated numbers of neighbouring NOTCH2-positive and HES1-positive BECs, which may be an important signalling relationship characteristic of Caroli disease patients." (PMID 37605966, 2023). "In tissues from Caroli disease and PLD patients, NOTCH receptors and ligands are expressed by cystic epithelial cells in which HES1 accumulates in the nucleus." (PMID 37605966, 2023).
cervical dysplasia (1 paper, 2019). "The comparison between HPV-16 and HES1 expression was significant in precancer (cervical intraepithelial neoplasia grades 1 to 3; P = .013), ISCC (International Federation of Gynecology and Obstetrics stages I to IV; P = .001), and ADC (P = .007)." (PMID 30615540, 2019). "This study showed that among all HPV-16–positive precancers, the major HES1 positivity signal arises from cervical intraepithelial neoplasia grades 2 and 3 that develops into ISCC." (PMID 30615540, 2019). "High sensitivity and specificity of nuclear HES1 in precancer, ISCC, and ADC strongly support its clinical significance for early detection, progression, and monitoring of patients with cervical dysplasia." (PMID 30615540, 2019).
childhood cancer (1 paper, 2022). "Future investigations will interrogate the molecular nature of YAP1 and HES1 convergence on CDKN1C, the transcriptional program governed by HES1 in FN‐RMS tumorigenesis, and the impact on FN‐RMS cell fate decisions, informing potential therapeutic opportunities for this childhood cancer." (PMID 36037042, 2022).
cholestasis (1 paper, 2025). Impairment of the bile flow caused by obstruction within the liver, or outside the liver in the bile duct system. "Opn+ hepatocytes appeared less abundant compared to Sox9 or Hes1 in all models, with the highest frequencies in cholestasis (BDL and DDC)." (PMID 41290681, 2025).
chronic kidney disease (1 paper, 2022). Impairment of the renal function secondary to chronic kidney damage persisting for three or more months. "Hes1 was reported to bind directly to the Ppargc1a promoter region and inhibit PGC-1α expression in animal models of chronic kidney disease (CKD)." (PMID 35225153, 2022).
chronic lymphocytic leukemia (1 paper, 2025). "Hes1 is overexpressed in B lymphocytes from peripheral blood samples of patients with chronic lymphocytic leukemia (CLL), and its expression positively correlates with the clinicopathological staging of CLL patients." (PMID 40755759, 2025). "For example, upon Hes1 silencing, the proportion of MEC1 and HG3 chronic lymphocytic leukemia cells arrested in the G1 phase increased, whereas the proportion in S phase decreased." (PMID 40755759, 2025).
chronic lymphoid leukemia (1 paper, 2021). "Jag1Ab attenuated the H. pylori-induced mRNA expression of Hes1, suggesting the inhibition of Notch signaling, which corresponded to the study in which the addition of Jagged1 antibody effectively blocked the axis of the Jagged1-Notch signaling pathway in chronic lymphoid leukemia." (PMID 34305857, 2021).
Cirrhosis (1 paper, 2022). A chronic disorder of the liver in which liver tissue becomes scarred and is partially replaced by regenerative nodules and fibrotic tissue resulting in loss of liver function. "In addition, we found that the expression level of miR-148a-5p in liver tissue of patients with cirrhosis was significantly decreased with the increase of Notch2 and Hes1 compared with the normal liver." (PMID 35883205, 2022).
colorectal adenocarcinoma (1 paper, 2023). The most common type of colorectal carcinoma. "Additionally, a previous study noted that loss of nuclear expression of HES1 in colorectal adenocarcinoma was markedly associated with female sex, right-sided location, BRAFV600E mutation, microsatellite instability, larger tumor size, and worse survival." (PMID 37957183, 2023).
colorectal adenoma (1 paper, 2020). An adenoma that arises from the colon or rectum. "We investigated mRNA expression of four Notch receptors (Notch1–4), five ligands (Jag1, Jag2, Dll1, Dll3, and Dll4), and four target genes (Hes1, Hes5, Hey1, and Hey2) using highly specific TaqMan gene expression assays in colorectal adenomas and cancers." (PMID 32211044, 2020).
congenital heart disease (1 paper, 2021). A heart disease that is present at birth. "Variants in the HES1 coding sequence are known to be associated with congenital heart disease (CHD)." (PMID 33585489, 2021).
deafness (1 paper, 2023). An inherited or acquired condition characterized by the complete loss of the ability to hear from one or both ears. "Moreover, the inclusion among the DEGs of genes involved in inner ear development and deafness (Atoh1, Edn1, Hes1, Kl, Myc, Mycn and Olig1) suggested their interaction with Dmp1 in these processes." (PMID 37106825, 2023).
developmental disabilities (1 paper, 2023). "According to previous reports, the miR-100 gene take part in the notch pathway and activates HES1, indicating that it is an important regulatory factor in developmental disabilities and the cellular growth cycle." (PMID 36644163, 2023).
diabetic neuropathy (1 paper, 2019). A chronic, pathological complication associated with diabetes mellitus, where nerve damages are incurred due to diabetic microvascular injury involving small blood vessels that supply these nerves, resulting in peripheral and/or autonomic nerve dysfunction. "Data in this study are consistent with a study that investigated Hes1 mRNA expression following diabetic neuropathy." (PMID 31454988, 2019).
dyslipidemia (1 paper, 2020). "Glucocorticoid inhibition of hairy enhancer of split 1 (Hes1) gene expression that regulates hepatic production of pancreatic lipase is also involved in the pathogenesis of dyslipidemia." (PMID 33633684, 2020).
endometriosis (1 paper, 2022). The growth of functional endometrial tissue in anatomic sites outside the uterine body. "HES-1 is an important Notch-dependent transcription factor that has been linked to epithelial–mesenchymal transition, cell proliferation, migration, and invasion in endometriosis." (PMID 35269992, 2022). "In contrast, the transcription factor HES-1 is overexpressed in patients with endometriosis compared to the healthy samples." (PMID 35269992, 2022).
endothelial dysfunction (1 paper, 2020). In vascular diseases, endothelial dysfunction is a systemic pathological state of the endothelium (the inner lining of blood vessels) and can be broadly defined as an imbalance between vasodilating and vasoconstricting substances produced by (or acting on) the endothelium. "In conclusion, we showed that the effect of ticagrelor related to the mitigation of endothelial dysfunction in stable CAD/COPD patients may be mediated, at least in part, by its capacity to increase SIRT1 and HES1 mRNAs levels." (PMID 32106619, 2020). "In patients treated with ticagrelor or clopidogrel, we observed a negative correlation among changes in both SIRT1 and HES1 mRNA and serum levels of Epidermal Growth Factor (EGF), a marker of endothelial dysfunction found to be reduced by ticagrelor treatment in our previous study." (PMID 32106619, 2020).
enteritis (1 paper, 2018). Inflammation of the small intestine. "Expression of some of the previously identified enteropathy markers was however regulated opposite to what would be expected during enteritis in AB1h or A22h (Ig mu chain C, Hes-1, Cebpz), or was also affected in the R23h line (IGKV4-1, MMP-9)." (PMID 30063731, 2018).
Fabry disease (1 paper, 2018). Fabry disease (FD) is a progressive, inherited, multisystemic lysosomal storage disease characterized by specific neurological, cutaneous, renal, cardiovascular, cochleo-vestibular and cerebrovascular manifestations. "In contrast to immortalized human podocytes exposed to lyso-Gb3, expression levels of COL4, FN1, HES1, and TGFβ1 were not elevated in urine-derived cells of Fabry disease patients." (PMID 30038331, 2018).
glaucoma (1 paper, 2017). Increased pressure in the eyeball due to obstruction of the outflow of aqueous humor. "Then it would also be important to prove HES1 target and the proposed molecular mechanism in an animal model of experimental glaucoma, such as the rat model induced by laser photocoagulation on TM." (PMID 28423527, 2017).
head neck cancer (1 paper, 2016). "Data retrieved from TCGA head neck cancer dataset suggested that DNA copy number of HES1, a putative downstream target of NOTCH1, significantly increased in human HNSCC than in its control counterpart (P = 1.06E-51)." (PMID 27108536, 2016).
Hodgkins lymphoma (1 paper, 2005). A heterogeneous group of malignant lymphoid neoplasms of B-cell origin characterized histologically by the presence of Hodgkin and Reed-Sternberg (HRS) cells in the vast majority of cases. "The Hodgkin's lymphoma cell line L540 served as positive control for Notch 1-EC expression and in vitro translated mHESl cDNA for HES1 protein expression." (PMID 16136053, 2005).
IgA nephropathy (1 paper, 2023). "Some scholars found that the expressions of Notch1 and Jagged1 were significantly upregulated in the kidney tissues of IgA nephropathy, and Notch1, HEY1, and HES1 were significantly reduced after administration of the Notch1 pathway inhibitor DAPT, thereby alleviating RIF." (PMID 36793762, 2023).
infantile hemangiomas (1 paper, 2011). "After analysis of eight members of the HES/HEY family, we found that HES1, HEY1, HEY2 and HEYL are expressed in infantile hemangiomas." (PMID 21834989, 2011). "Moreover, HES and HEY transcripts are affected by Compound E, a gamma secretase with consistent down-regulation of HES1, showing that NOTCH signaling occurs in infantile hemangiomas." (PMID 21834989, 2011).
Insulin resistance (1 paper, 2019). Increased resistance towards insulin, that is, diminished effectiveness of insulin in reducing blood glucose levels. "J 2 (JAG2), NOTCH3, CDKN1A, HES1, and MAPT are novel biomarkers for the development of insulin resistance." (PMID 30678306, 2019).